INS (insulin)
Diseases named in the same sentence as INS in open-access papers (continued):
Sharing a sentence is not in itself a finding about the gene and the disease.
diabetes (continued). "Diabetes, particularly type 2 diabetes (T2D), is characterized by the deficiency of insulin caused by pancreatic β-cell dysfunction and insulin resistance in target organs." (PMID 40136728, 2025). "In our study, we found that being physically active in the past 30 days was inversely associated with diabetes, aligning with established protective effects of exercise on glucose metabolism, insulin sensitivity, and weight management." (PMID 41464450, 2025). "In contrast, type 2 DM (T2DM), which accounts for the majority of diabetes cases, is characterized by insulin resistance and a relative deficiency in insulin secretion." (PMID 40625489, 2025). "Hyperglycemia is the hallmark in both types of diabetes and is the direct consequence of insulin dysfunction." (PMID 41030912, 2025). "This cross-sectional study found that HbA1c levels were associated with the accessibility of modern diabetes technologies and insulin." (PMID 40864470, 2025). "The dysfunction of beta cells in the pancreas leads to irregularities in insulin levels, abnormal blood glucose concentration, insulin insufficiency, and insulin resistance." (PMID 40356976, 2025). "Diabetes Mellitus (DM) is delineated as a multifaceted metabolic disorder characterized by chronic hyperglycemia stemming from deficiencies in insulin action or production." (PMID 41370415, 2025). "A heterozygous variant (NC_000011.10(NM_000207.3) (INS):c.277G>A p.Glu93Lys) was identified in an 11-year-old patient who presented with mild diabetic ketoacidosis, strong family history of diabetes and low C-peptide, suggesting insulin deficiency." (PMID 39717432, 2025). "Insulin therapy remains a cornerstone of diabetes management but is associated with weight gain and an increased risk of hypoglycemic episodes." (PMID 41309777, 2025). "Second, epigenetic modifications can affect gene expression related to metabolic pathways (e.g., insulin signaling, adipogenesis, and lipid metabolism), increasing susceptibility to obesity and diabetes later in life." (PMID 39354115, 2025). "Currently, diabetes therapy is focused on pharmacological interventions such as gluconeogenesis inhibitors, insulin sensitizers, and weight-loss medications." (PMID 40001488, 2025). "We evaluated the risk of AGT (i-IGT, i-IFG, IFG+IGT and diabetes) using both the insulin demand–adequacy method and the RAD method based on follow-up glucose tolerance records." (PMID 39611962, 2025). "In fact, CypD plays a key role in ischemia–reperfusion injury, atherosclerosis, and diabetes, and regulates the pore to face a high-fat diet treatment causing mitochondrial dysfunction and insulin resistance." (PMID 40199808, 2025). "Two OA risk factors (diabetes, smoke) and insulin (ukb-b-7350) were separately used to construct models to predict the relationship between the 2 risk factors and the outcomes." (PMID 41398760, 2025). "Diabetes alters membrane composition across cell types, increasing rigidity and impairing membrane-associated protein function (including insulin secretion)." (PMID 41009376, 2025). "Enrichment is greatest in the first two years after diabetes onset and is amplified by clinical flags such as more than 5% weight loss, a rapid HbA1c rise, a new insulin requirement, or therapy intensification." (PMID 41226286, 2025). "This suggests that BCS is effective in improving insulin secretion by restoring pancreatic β-cell damage caused by diabetes mellitus." (PMID 40002361, 2025). "Specifically, serum zinc was significantly lower in patients with serum ferritin above 2,500 ng/mL, a finding associated with impaired insulin secretion and an increased risk of diabetes mellitus." (PMID 41393748, 2025). "T1DM is an autoimmune disease characterized primarily by decreased insulin secretion, while T2DM is characterized by reduced insulin sensitivity and relative insulin deficiency, accounting for over 90% of all diabetes cases." (PMID 40296350, 2025).
diabetes (continued). "In our cohort of over 1000 patients, we observed that non-insulin-treated diabetes was more strongly associated with the prevalence of dilated cardiomyopathy (DCM) than either insulin-treated diabetes or obesity alone." (PMID 41153651, 2025). "Diabetes mellitus (DM) is primarily characterized by chronic hyperglycemia resulting from impaired insulin production or function and is associated with a variety of serious complications." (PMID 41180198, 2025). "For example, Wendan decoction has been shown to improve multiple diabetes indicators, such as BMI, fasting insulin, and blood lipids, through pathways associated with oxidative stress and inflammation." (PMID 41354800, 2025). "Chronic insulin resistance induces progressive β-cell dysfunction, ultimately leading to impaired insulin secretion, elevated blood glucose levels, and consequently increased diabetes risk." (PMID 41255531, 2025). "Emerging epidemiological data also indicate that Indians are at higher risk of impaired insulin secretion, adding a further burden to the diabetes incidence among South Asians." (PMID 39843936, 2025). "Myostatin inhibition when used in conjunction with insulin treatment improves muscle mass and trabecular bone properties in a mouse model of insulin-deficient diabetes in female mice." (PMID 40575255, 2025). "Ceramides, particularly, have been associated with the inflammatory response in diabetes where they trigger Caspase‐1 activation and IL‐1β secretion impairing insulin sensitivity." (PMID 39327931, 2025). "Insulin resistance, diabetes, and low insulin levels are all correlated with an increased risk of cognitive decline." (PMID 40491970, 2025). "Inhibition of myostatin, a negative regulator of muscle mass, was explored as a druggable target to improve the musculoskeletal phenotype associated with insulin-deficient diabetes in female mice." (PMID 40575255, 2025). "Suboptimal temperature is positively associated with diabetes incidence and mortality and has a significant effect on insulin sensitivity." (PMID 40951432, 2025). "His laboratory has notably contributed to understanding how mitochondrial dysfunction and irregular insulin signaling heighten the risk of heart failure in diabetes." (PMID 40598681, 2025). "Regarding the frequency of blood glucose testing, the American Diabetes Association guidelines recommend that patients using intensive insulin regimens should be encouraged to monitor glucose levels using SMBG (and/or CGM) at least once every eight hours." (PMID 41458677, 2025). "An acquired or inherited incapacity of the pancreatic tissue to produce insulin causes diabetes mellitus (DM), a well-known endocrine disorder." (PMID 41394924, 2025). "IRS proteins are key molecular that regulates insulin signaling pathways and is strongly associated with the development of diabetes, while diabetes has been shown to be a risk factor for a significantly increased risk of stroke." (PMID 40264650, 2025). "Impaired glucose-stimulated insulin secretion (GSIS) is a hallmark of β cell dysfunction in diabetes." (PMID 41052246, 2025). "IAH is a common and disabling complication of insulin-treated diabetes, which predisposes people to a significantly increased risk of SH compared to people with NAH." (PMID 40520684, 2025). "In numerous studies on diabetes, in rats with diabetes caused by streptozotocin, D-pinitol has been demonstrated to increase the insulin sensitivity of insulin target tissues." (PMID 39796627, 2025). "Research indicates that these diets improve insulin sensitivity, reduce HbA1c levels, and lower the risk of developing diabetes by up to 34%." (PMID 40062050, 2025). "Impaired insulin signaling, as the hallmark of diabetes mellitus, disrupts molecular pathways involving amyloid-β (Aβ) clearance and tau hyperphosphorylation, potentially contributing to synaptic dysfunction in AD." (PMID 40964391, 2025).
diabetes (continued). "The second most important factor was age, which is a well-known risk factor for diabetes due to age-related declines in insulin sensitivity and beta-cell function." (PMID 40988175, 2025). "We explore the physiological role of the IL-1β pathway in insulin secretion and the relationship between circulating levels of IL-1β and the development of diabetes and associated diseases." (PMID 39496966, 2025). "Further studies evaluating the influence of healthcare workers on PIR among patients with diabetes mellitus are important, as healthcare workers have been implicated in delays to initiating insulin therapy on patients (clinical inertia)." (PMID 40336418, 2025). "The loss of β-cells further diminishes insulin secretion, thus accelerating the development of diabetes." (PMID 40458823, 2025). "Studies have found that obesity makes the body less sensitive to insulin, causing diabetes, and also worsens kidney disease by increasing pressure in the kidneys and hyperfiltration." (PMID 40235535, 2025). "Primary: change in HbA1c at 24 weeks.Significant HbA1c reduction, weight loss, and lower insulin dose vs. placebo.Increased risk of diabetic ketoacidosis." (PMID 41551500, 2025). "Our study will evaluate the role of microplastics in the aetiology of diabetes mellitus, as well as the association between microplastic exposure and insulin pen use." (PMID 41304478, 2025). "These interventions not only help reduce blood lipid levels but also reduce the risk of diabetes by improving insulin sensitivity and overall metabolic function, providing a comprehensive clinical management strategy." (PMID 40842495, 2025). "RORα plays a role in controlling blood glucose homeostasis and the development of diabetes by modulating gluconeogenesis and is also closely associated with lipogenesis, insulin production, and insulin sensitivity." (PMID 40427539, 2025). "Background and Objectives: Diabetes mellitus is a prevalent chronic disease caused by inadequate insulin secretion or ineffective insulin response, leading to complications such as retinopathy, nephropathy, heart attacks, and strokes." (PMID 40005351, 2025). "pMSC density was reduced around insulin-deficient islets compared with insulin-containing islets in individuals with diabetes (p<0.001), consistent with an islet-protective role for pMSCs." (PMID 41422462, 2025). "We identified significant associations between diabetes distress and young age at diabetes onset, insulin use, and a history of diabetes foot ulcer." (PMID 39972441, 2025). "The analysis revealed that age, use of oral antidiabetic drugs, insulin therapy, educational level, income, and duration of diabetes were significantly associated with HbA1c control (p< 0.05)." (PMID 40979703, 2025). "Because inflammation is linked to decreased insulin sensitivity, it is assumed to be a significant factor in the development of type 2 diabetes mellitus." (PMID 40541974, 2025). "Insulin signaling abnormalities are an established hallmark in older adults with pre-diabetes/T2DM and have also been observed in PD." (PMID 40088335, 2025). "This challenge is compounded by the increased risk of hypoglycaemia associated with intensive insulin therapy, meaning that even individuals who actively manage their diabetes often fail to achieve optimum glycemic targets." (PMID 40718205, 2025). "These analyses, stratified by age, gender, ethnicity, cardiovascular history, heart failure, hyperlipidemia, hypertension, diabetes duration, HbA1c levels, and insulin treatment, showed consistent associations across all categories." (PMID 41459091, 2025). "The two primary types of diabetes have distinct causes: Type 1 diabetes occurs when the pancreas produces insufficient insulin due to damaged beta cells, while Type 2 diabetes results from the body’s inability to effectively use the insulin it produces." (PMID 40136949, 2025).
diabetes (continued). "Elevated blood glucose due to insufficient insulin or insulin resistance causes a serious metabolic disease called diabetes mellitus." (PMID 40771585, 2025). "Elevated Cer in muscle tissue was associated with increased risk of diabetes, higher body fat ratio and lower insulin sensitivity in men." (PMID 40980166, 2025). "Insufficient sleep negatively affects glucose regulation by impairing insulin sensitivity and increasing insulin resistance, contributing further to diabetes risk." (PMID 41516982, 2025). "As a negative regulator of insulin sensitivity, microbiota-dependent leptin modulation offers novel therapeutic targets for ameliorating diabetes-associated gastrointestinal symptoms." (PMID 40861487, 2025). "In PTDM, CNI immunosuppressant agents causing insulin secretory dysfunction are attributed as the main risk factor for developing diabetes." (PMID 40664615, 2025). "A case-control study revealed that metformin significantly lowered the risk of PDAC in diabetic patients, whereas the use of insulin or insulin secretagogues was linked to a higher PDAC risk in individuals with diabetes." (PMID 39948335, 2025). "Reduced levels of cytokines, along with inflammatory markers like C-reactive protein, highlight the role of weight loss in diabetes remission through improved glucose absorption and insulin function." (PMID 40005466, 2025). "The World Health Organization (WHO) estimates that 830 million individuals experience the ill effects of diabetes, a condition described by ongoing hyperglycemia because of insulin resistance or deficiency in insulin secretion." (PMID 40677508, 2025). "In summary, prior literature has indicated the involvement of PAM deficiency in impaired insulin secretion and diabetes and potentially in excess GH secretion." (PMID 39137152, 2025). "Prescriptions for insulin, antiplatelet, and anticoagulant agents serve as surrogate markers for underlying diabetes, thrombotic risk, and pre-existing comorbidities." (PMID 41351012, 2025). "Hormonal differences, such as the influence of androgens, affect insulin sensitivity and fat distribution, thereby increasing diabetes risk in males." (PMID 39752048, 2025). "Higher pre-pregnancy weight, family history of diabetes, insulin resistance markers, and co-morbid conditions were significantly linked to insulin requirement." (PMID 41623786, 2025). "Diabetes is a chronic disorder characterized by elevated blood glucose levels, caused by either inadequate insulin production in the pancreas or resistance to insulin." (PMID 40171822, 2025). "Others have used a similar approach to understand how β cell development and health are affected by insulin mutations or SNPs derived from monogenic patients, neonatal diabetes patients, and GWAS studies." (PMID 41480350, 2025). "Pathway enrichment analysis revealed that risk genes associated with glycemic traits are involved in insulin secretion and diabetes." (PMID 40399988, 2025). "The most common cause of hyperglycaemia is diabetes mellitus, in which there is impaired insulin production (type 1 diabetes) or resistance to the peripheral actions of insulin (type 2 diabetes)." (PMID 40650241, 2025). "All types of diabetes are characterised by beta cell dysfunction and loss leading to critical deficiencies in insulin, and subsequently aberrant metabolic regulation of key energy substrates." (PMID 40133488, 2025). "Beyond the glucose control by oral drugs and insulin, the American Diabetes Association guideline has highlighted that how to optimize lifestyle behavior to improve diabetes care is worthy of attention, especially for high‐genetic‐risk groups." (PMID 40931579, 2025). "To address these gaps, we conducted a larger non-randomized clinical trial to evaluate the short-term effects of an LCD compared to a low-fat control (CON) diet on GV in hospitalized patients with endogenous-insulin-deficient diabetes." (PMID 41586239, 2025).
diabetes (continued). "Cardiometabolic related outcomes formed the bulk of our data (11/27); these studies found associations between prematurity and increased risk of diabetes, decreased insulin sensitivity, higher body fat percentage and dyslipidaemia." (PMID 41244257, 2025). "While hypothyroidism and obesity have been previously identified as modifiers of heart failure progression, our findings are novel in demonstrating that their specific combination with non-insulin-treated diabetes confers the highest structural cardiac risk." (PMID 41153651, 2025). "This association suggests that genetic factors contribute to insulin resistance pathways even before clinical diabetes onset, offering mechanistic insights into how genetic predisposition translates into disease risk." (PMID 41034193, 2025). "This is important as it can help reduce the risk of various chronic diseases, such as type 2 diabetes by improving insulin sensitivity, regulating blood glucose levels, and reducing the risk of developing diabetes." (PMID 40894207, 2025). "Just as diabetes, which is the product of an insulin deficiency, is treated by administering insulin, so depression, which is the product of a serotonin deficiency, is treated by administering a drug that enhances its brain availability—this is the leitmotif." (PMID 40141399, 2025). "Because TXNIP is strongly associated with impaired insulin secretion and β-cell apoptosis in diabetes models, inactivation of TXNIP is being pursued clinically for both T1D and T2D treatments." (PMID 40136648, 2025). "SU also provides better glycemic control with a reduction in HbA1c by an average of 2.2% in the first year after the switch from insulin to SU, an increase in C-peptide plasma levels, and a reduction in the risk of complications associated with diabetes." (PMID 41169283, 2025). "HUA is an independent risk factor for the onset of diabetes through the promotion of inflammatory responses and oxidative stress, thereby impairing insulin sensitivity." (PMID 41473239, 2025). "There are two types of diabetes mellitus, one is Type1 Diabetes (T1D) caused due to insufficient level of insulin in the blood cell." (PMID 39827098, 2025). "IR is commonly attributed to impairments in glucose metabolism within tissues mediated by insulin, serving as a significant pathological basis for underlying metabolic disorders like diabetes and obesity." (PMID 40979713, 2025). "These compounds exhibit a combination of antioxidant, anti-inflammatory, and insulin-sensitizing properties, all of which are crucial for mitigating the complications associated with diabetes." (PMID 40686811, 2025). "The most well-known mechanism for the development of sarcopenia in individuals with diabetes is the loss of anabolic effects on skeletal muscle due to insulin deficiency or reduced insulin sensitivity." (PMID 40731782, 2025). "In the downregulated genes, however, KEGG results indicated a strong correlation between these genes and diabetes mellitus, prominently among them Ins1 and Ins2, the 2 insulin encoding genes." (PMID 40906536, 2025). "Type 2 diabetes mellitus (T2DM), predominantly caused by insulin resistance and often due to insufficient insulin secretion from pancreatic β-cell deterioration, is most common in individuals over 40 and accounts for over 90% of diabetes cases." (PMID 40406527, 2025). "Quercetin-induced changes in adipose tissue are associated with the alleviation of diabetes-related disturbances, such as excessive fat accumulation, impaired insulin action, and elevated blood adipokine levels." (PMID 40806520, 2025). "Despite that, patients carrying this protective variant showed lower insulin autoimmunity, residual β cell function, higher C-peptide levels, better glycemic control, and a lower risk for diabetes complications." (PMID 41480350, 2025).